VEGFA (vascular endothelial growth factor A)
Diseases named in the same sentence as VEGFA in open-access papers (continued):
Sharing a sentence is not in itself a finding about the gene and the disease.
prostate carcinoma (continued). "A consistent increase in VEGFA expression has been observed in primary tumor specimens as well as serum samples from prostate cancer patients." (PMID 26019137, 2015). "Seems to be contradictory, a latest study in prostate cancer reported that KLF5 inhibited angiogenesis in PTEN-deficient prostate cancer by attenuating Akt activation and subsequent HIF1-maintained VEGFA expression." (PMID 26544730, 2015). "In order to assess the efficacy of SRPK1 inhibition by SPHINX on substrate phosphorylation, we previously showed that the treatment of PC3 prostate cancer cells with SPHINX led to reduced levels of phosphorylated SR proteins coinciding with increased expression of anti-angiogenic VEGFA." (PMID 36895328, 2023). "Furthermore, significant changes in VEGF signaling were detected in aggressive PC-3 prostate carcinoma cells, resulting in early (4 h s-μg) and late (3 days to 5 days s-μg) downregulation of VEGFA expression, indicating attenuation of PC-3 aggressiveness." (PMID 35887223, 2022). "Therefore, the epigenetic switch is critical for regulating the expression of metastasis-linked factors, including Slug, CD44, VEGFA, and EGFR, which, in turn, modulate the invasiveness of prostate cancer cells." (PMID 33670804, 2021). "Interestingly, it was found that the expression of VEGFA is negatively correlated with the copy number of BTG3 in prostate cancer." (PMID 33311481, 2020). "Moreover, MMSET interacts with NF-κB directly to activate the expression of NF-κB target genes (including interleukin-6, vascular endothelial growth factor A, cyclin D, Bcl-2 and Survivin) in prostate cancer cells." (PMID 29796186, 2018). "Interestingly, five pathways, the Notch signaling pathway, receptor tyrosine kinase/PDGF signaling pathway, TGF-β signaling pathway, VEGFA signaling pathway, and Wnt signaling pathway, were in common in both S:E fusion-positive and T:E fusion-positive prostate cancers." (PMID 36579559, 2022). "In prostate cancer, LSD1 binds to the promoter region of VEGF-A (vascular endothelial growth factor A) to regulate the protein level via AR, and VEGF-A partially promotes cell invasion and metastases by inducing epithelial–mesenchymal transition." (PMID 40028036, 2025). "In castration-resistant prostate cancer cells, NSD2-mediated H3K36me2 upregulates the expression of vascular endothelial growth factor-A (VEGF-A), a key regulator of angiogenesis." (PMID 41301842, 2025). "NR2F2 (COUP-TFII) plays a critical role in mediating the effects of DHA treatment on EFNB2, EBF1, ETS1, and VEGFA expression, and the knockdown of NR2F2 can recede the functional changes induced by DHA treatment in prostate cancer cells." (PMID 39364872, 2025). "TNF-mediated NF-B/VEGFA axis is able to contribute to tumor angiogenesis, and autocrine HIF-1 and TNF increase the invasive potential of prostate cancer cells PC3 in a hypoxic tumor microenvironment." (PMID 37064125, 2023). "In prostate cancer cells, TNF-α induces VEGFA expression by activating downstream NF-κb signaling, and promotes endothelial cell angiogenesis." (PMID 32993787, 2020). "We found that the supernatant of PC3 prostate cancer cells promoted the expression of CD206, VEGFA and EGF in THP‐1 indicating the polarization of TAM." (PMID 32469149, 2020). "In prostate cancer, elevated expression of LSD1 correlates with prostate cancer recurrence and with increased VEGFA expression, and knockdown of LSD1 in prostate cancer cells decreases VEGFA expression." (PMID 32070413, 2020). "For example, microRNA-34a inhibits prostate cancer stem cells and metastasis by directly repressing CD44, while miR-203 suppresses tumor growth and angiogenesis by targeting VEGFA in cervical cancer." (PMID 28030804, 2017). "In addition, in prostate cancer, CAV1 affects lymphangiogenesis mediated by the panangiogenic factor vascular endothelial growth factor A (VEGFA)." (PMID 36067135, 2022).
prostate carcinoma (continued). "LGALS3BP has earlier been shown to be upregulated in human colorectal and prostate cancer which may influence oncogenesis and promote cancer growth and angiogenesis through the PI3K/AKT/VEGFA pathway." (PMID 36497496, 2022). "In the balanced differentiated group of young and old prostate cancer patients, MYC and HDAC1 genes were emerged as a central node and uniquely upregulated in young men whereas VEGFA is the key node in old men and found to be down regulated along with HLA and ANXA2 genes in old patients." (PMID 33575208, 2020). "Pro- and anti-angiogenic VEGFA splice isoforms are not the only VEGFA splice isoforms that are biologically significant in prostate cancer." (PMID 29693622, 2018). "Interestingly, we found that PKCζ regulates the expression of VEGFD, VEGFA, ANG1, and ANG4 in prostate cancer cells, which may facilitate the generation of aberrant lymphangiogenesis in tumors." (PMID 30705401, 2019). "In DU145 prostate carcinoma cells cultured without glucose, JNK was shown to act upstream of AMPK pathway to increase VEGFA mRNA stability." (PMID 20824063, 2010).
ischemia (480 papers, 2006 to 2026). A hypoperfusion of the BLOOD through an organ or tissue caused by a PATHOLOGIC CONSTRICTION or obstruction of its BLOOD VESSELS, or an absence of BLOOD CIRCULATION. "The underlying stress leading to the induction of new vessel growth is mainly a result of ischemia but also inflammation, which causes the induction of angiogenic factors, including vascular endothelial growth factor A (VEGF-A), by local tissue resident cells." (PMID 33671954, 2021). "Macrophages appear to be a critical source of proangiogenic vascular endothelial growth factor A (VEGF-A) during acute ischemia or in wound injury models." (PMID 40299401, 2025). "Studies have demonstrated that activation of the HIF‐1α‐VEGFA‐Notch1 signaling pathway promotes angiogenesis within the cerebral microvascular system, thereby protecting against ischemia–reperfusion injury in the brain." (PMID 40019048, 2025). "VEGFA-stimulated angiogenesis contributes to the functional and morphological recovery of ischemia tissues in terms of the supplement of oxygen and nutrients to the damaged tissue and is considered as indispensable for new fiber formation after muscle damage." (PMID 36977984, 2023). "Angiogenesis is mainly driven by ischemia and up-regulation of ischemia-induced transcription factors like HIF1a, and the genes that are responsive to these transcription factors, such as VEGFa and SDF1." (PMID 34630958, 2021). "Increases in the VEGFA immunoreactivity in hypertrophic astrocytes were observed in the penumbra area at 24 h after ischemia, and these increases persisted for at least 1 week." (PMID 25269821, 2014). "In summary, our data indicate that VEGFB and VEGFA and their receptors are up-regulated by candesartan in the brain after ischemia and the changes are seen differentially in both hemispheres." (PMID 21912702, 2011). "This corresponds well to the increased activity of the prosurvival VEGFB in the area of the ischemia and the more proangiogenic VEGFA on the contralateral side." (PMID 21912702, 2011). "Vascular endothelial growth factor-A (VEGF) is essential for embryonic vasculogenesis and for angiogenesis in a variety of important pathologies including ischemia and wound repair, proliferative retinopathies, psoriasis, rheumatoid arthritis, and cancers." (PMID 21049044, 2010). "Mechanistically, the protective effect of HSYA in alleviating myocardial injury after ischemia may be associated with NLRP3 inflammasome, Bcl-2, Bax, caspase-3, eNOS proteins, and TLR/NF-κB, Nrf2/HO-1, JAK/STAT, PI3K/Akt, AMPK/mTOR, VEGFA pathways." (PMID 40271057, 2025). "It remains to be determined whether other efferocytosis-triggered angiogenic factors besides VEGFC, such as VEGFA, promote lymphangiogenesis and vascular angiogenesis after ischemia." (PMID 35499075, 2022). "Changes in expression or altered function of CaSRs also affects CNS diseases, such as AD and ischemia/hypoxia/stroke, by regulating outward K+ channel fluxes, nitric oxide (NO) and vascular endothelial growth factor A (VEGF-A) overproduction, amyloidogenesis, glial activation, and neuronal death." (PMID 32498476, 2020). "Vision loss in retinopathy of prematurity and proliferative diabetic retinopathy are caused by several growth factors, including vascular endothelial growth factor-A (VEGF-A), the most potent cytokine that mediates ischemia-induced retinal neovascularization (NV) in ocular pathologies." (PMID 28455954, 2017). "Furthermore, our findings support the notion that PP2 inhibits the expression of VEGFA following ischemia." (PMID 25269821, 2014). "Furthermore, HSYA could upregulate VEGFA expression to promote angiogenesis in ischemic myocardium, thereby ameliorating ischemia-induced cardiac dysfunction and myocardial injury." (PMID 40271057, 2025).
ischemia (continued). "However, architecturally defective, poorly integrated vessels with blind ends are typical of pathological angiogenesis induced by vascular endothelial growth factor-A (VEGF), thereby limiting the utility of VEGF for therapeutic angiogenesis and aggravating ischemia-related pathologies." (PMID 21049044, 2010). "The pathophysiological basis likely involves ischemia-driven upregulation of non-vascular endothelial growth factor angiogenic factors (platelet-derived growth factor [PlGF], angiopoietin-2 [Ang-2]) that bypass VEGF blockade." (PMID 40969370, 2025). "VEGFa, SDF-1α, and FGF2 factors measured in the present study are responsible for angiogenesis, proliferation, migration, expressions of adhesion protein, and extracellular matrix reconstruction and are involved in initiating tissue repair and reperfusion following ischemia." (PMID 34367293, 2021).
Stroke (441 papers, 2007 to 2026). Sudden impairment of blood flow to a part of the brain due to occlusion or rupture of an artery to the brain. "VEGFA is implicated in the pathophysiology of atherosclerosis, and in stroke, VEGFA is elevated in the ischemic penumbra and mediates vessel and neuron repair and remote plasticity in ischemic brain regions." (PMID 34829993, 2021). "VEGFA, a main proangiogenic factor, plays a central role in vasculogenesis and neurogenesis and is associated with neurological function in stroke recovery." (PMID 34054530, 2021). "Notably, one of the common validated gene targets of miR-20a-5p and miR-206, VEGFA has been previously associated with stroke severity." (PMID 36613546, 2022). "At least the increases of VEGFA agree with the association of the risk of incident stroke/transient ischemic attack as well as the occurrence and development of cognitive impairment in stroke." (PMID 27635404, 2016). "The decrease in VEGFA within stroke patients is contrary to the existing literature which shows evidence of VEGFA increase after stroke." (PMID 41306424, 2025). "Aβ 40 (p = 0.005, Cliff’s d = 0.448), Aβ 42 (p < 0.001, Cliff’s d = 0.554), and VEGFA (p = 0.008, Cliff’s d = 0.459) were significantly elevated in control patients compared to stroke patients." (PMID 41306424, 2025). "In our study, the enhanced expression of VEGFA was observed in the ipsilateral hemisphere 7 days post-stroke, compared to in the contralateral hemisphere (p < 0.05)." (PMID 40332314, 2025). "GFAP (p < 0.001, Cliff’s d = 0.505) was increased in the stroke patients while AB 40 (p = 0.006, Cliff’s d = 0.363), Aβ 42 (p < 0.001, Cliff’s d = 0.450), and VEGFA (p = 0.005, Cliff’s d = 0.413) where increased in the control patients." (PMID 41306424, 2025). "Following a stroke, the organism increases the content of neovascularization factors like VEGFA, Ang-2, and bFGF during the initial and progressive phases." (PMID 38962303, 2024). "Intravenous administration of VEGFA during the acute phase of stroke, 1–24 h, leads to an increase in infarct size and BBB permeability." (PMID 37189449, 2023). "Animal models of stroke have largely shown that the administration of VEGFA has led to increased angiogenesis and infarct volume reduction." (PMID 37189449, 2023). "On the other hand, if VEGFA is administered intravenously in the late phase of stroke, 24 h after stroke onset, infarct size decreases." (PMID 37189449, 2023). "With careful consideration for the potential side effects, VEGFA has been administered as a treatment in various animal models for cerebrovascular diseases, such as head injuries and stroke." (PMID 37189449, 2023). "VEGFA has shown beneficial effects in animal models of cerebrovascular diseases like stroke and TBI, but similar beneficial effects have yet to be observed in humans." (PMID 37189449, 2023). "Direct application of VEGFA to the brain by surgically lifting a part of the skull to treat stroke has also been effective." (PMID 37189449, 2023). "Stroke induced a significant increase in VEGFA, VEGFR2, FGF2, and FGFR1 expression 1–3 days after MCAO." (PMID 34992208, 2022). "In mice after stroke, worse stroke‐related brain damage correlated with increased levels of VEGFA, which were both reversed by Uric Acid." (PMID 34693660, 2021). "Stroke pathology significantly affects angiogenesis by altering the levels of angiogenic factors (for instance, vascular endothelial growth factor A, VEGF-A) essential for vascular remodeling and functional recovery post-stroke." (PMID 34756133, 2021). "At 6 weeks after treatment, one patient had a stroke, which was diagnosed as a grade 3 adverse event; VEGFA amplification was detected in this patient’s specimen." (PMID 32631434, 2020). "We observed an increase in capillary density in the RV of swine with CTEPH compared to control, which correlated with the increased stroke work and was consistent with the trend towards increased VEGFA expression." (PMID 31194256, 2019).
Stroke (continued). "An increase in VEGFA protein in the contralesional hemisphere corresponded to a significant increase in vascular density at seven days (p<0.01) after stroke onset." (PMID 21912702, 2011). "Our initial finding of a proangiogenic factor in the CSF, only partly blocked by a VEGFA antibody, led us to studies aimed at determining the impact of these findings on both hemispheres after stroke." (PMID 21912702, 2011). "Similarly to Aβ, VEGFA expression was lower in the stroke population compared to the control population." (PMID 41306424, 2025). "Fortunately, VEGFA treatment has been shown to be beneficial to stroke recovery in animal models." (PMID 37189449, 2023). "Similar to tPA that has a short window of effect during the early phase of stroke before it becomes detrimental, VEGFA isoforms may have similar constraints or they may have multiple periods where there therapeutic use can be maximized." (PMID 37189449, 2023). "Interestingly, combined administration of VEGFA and perlecan improved stroke outcomes in a murine model of stroke." (PMID 37189449, 2023). "Notably, levels of VEGFA also increase with the severity of stroke, Alzheimer’s Disease (AD), and traumatic brain injury (TBI)." (PMID 37189449, 2023). "ET-1 (the major isoform of endothelins) and VEGFA, which have been both reported to play a key role in the pathogenesis of atherosclerosis, cardiovascular disease and stroke, may provide potential novel therapeutic targets." (PMID 35755441, 2022). "Indeed, multiple Hypoxia-inducible factor 1alpha (HIF-1α)-induced miRNAs, called hypoxia-regulated microRNAs (HRMs), have been shown to modulate post-stroke angiogenesis by targeting the vascular endothelial growth factor A (VEGF-A) pathway." (PMID 30678250, 2019). "Thus, Wnt/HIF1α signaling in mature ECs may not be critical for barrier formation, but may play an indirect role in a context-dependent manner, for example via HIF1α/VEGFA signaling during hypoxic conditions in diseases such as stroke and cSVD." (PMID 38147228, 2024). "Treatment with VEGFA coupled with stem cells may show therapeutic effects in animal stroke models." (PMID 34829993, 2021). "In addition, genome-wide association studies (GWAS) have associated variants in VEGFA with coronary heart disease and myocardial infarction, and variants in other gene targets of miR-20a-5p, CDKN1A (also a common gene target of miR-181a-5p) and PRKG1 with stroke." (PMID 36613546, 2022). "Neutralization of IL-9 ameliorates post-stroke damage to the blood-brain barrier (BBB) via down-regulating astrocyte-derived VEGF-A, which suggested VEGFA as a novel therapeutic target of immune intervention of IS." (PMID 35419038, 2022). "The core targets of PPI are TNF,IL-6,ALB,AKT1,VEGFA, and CREB1, which play a key role in the regulation of stroke by DZSM." (PMID 34754318, 2021). "In this study, we observed that MMP-3/9 and VEGFA expression were downregulated in EC-TXNIP KO mice with HG and tPA-reperfusion, which correlates with improved BBB function after embolic stroke." (PMID 34681207, 2021). "Our results support the concept that tPA-reperfusion in HG mice promotes HT and BBB damage after embolic stroke, possibly through TXNIP and upregulating MMP-3/9, and VEGFA expression." (PMID 34681207, 2021). "Overall, main FD features including hypertrophic cardiomyopathy, venous thrombosis, arterial thrombosis, and stroke, cornea verticilata, and renal (chronic kidney disease stage) events are partly explained by FGF2, IL-7, VEGFA, and VEGFC plasma levels." (PMID 32370284, 2020). "In our study, we only focused on the effects of VEGFA,VEGFB and their corresponding receptors to stroke recovery." (PMID 21912702, 2011). "Since our earlier work suggested a proangiogenic effect in the CSF, we compared the concentrations of VEGFA and VEGFB in the CSF of both candesartan and saline treated animals at 24 hours after stroke." (PMID 21912702, 2011).
Stroke (continued). "In this study, hypoglycemia did not result in changes in VEGFA, ICAM1, ICAM2 and VCAM1 as known mediators of endothelial dysfunction associated with atherosclerosis, stroke and myocardial infarction, as well as T2D microvascular complications." (PMID 41596469, 2026). "Although VEGFA does not belong to the group of DAMPs, determining its expression is important in the context of the pro-angiogenic changes that occur after stroke." (PMID 40332314, 2025). "The core targets of DZSM for stroke are TNF, AKT1, VEGFA, and IL-1β, which are highly correlated." (PMID 34754318, 2021). "Vascular restoration by candesartan after stroke maybe related to differential regional upregulation of VEGFB and VEGFA, promoting a “prosurvival state” in the ischemic hemisphere and angiogenesis in the contralesional side, respectively." (PMID 21912702, 2011). "We detected no hint of increased gene expression of VEGFA after stroke and candesartan, however." (PMID 21912702, 2011). "Our earlier report of increased VEGF in the ischemic hemisphere of candesartan treated animals, reflected the inability of the nonspecific ELISA assay to differentiate between VEGFA and VEGFB and is a more common way to report VEGF quantification in the stroke literature." (PMID 21912702, 2011).